SCARNA20 (small Cajal body-specific RNA 20)
Synonyms: ACA66
Gene: Small Cajal body-specific RNA gene on chromosome 17 (60,231,516 to 60,231,646, reverse strand). Ensembl gene ENSG00000252577.
Gene Ontology:
Biological process: RNA processing
Cellular component: Cajal body; nucleolus
Homologues: Orthologues: chimpanzee SCARNA20 (100% identical).
Diseases named in the same sentence as SCARNA20 in open-access papers:
SCARNA20 is named in the same sentence as 1 disease in open-access papers, as found by Europe PMC text mining. Sharing a sentence is not in itself a finding about the gene and the disease.
SCARNA20 shares sentences with these, for which no sentence is quoted: tumor (1 paper).